CEMIP (cell migration inducing hyaluronidase 1)
Diseases named in the same sentence as CEMIP in open-access papers (continued):
Sharing a sentence is not in itself a finding about the gene and the disease.
colon carcinoma (23 papers, 2011 to 2024). "In colon cancer cells, the expression of CEMIP influences the expression of genes linked to cell-cycle regulation, proliferation, migration, and apoptosis." (PMID 36291875, 2022). "We identify CEMIP as a secreted protein that is induced as early as the colon adenoma stage, whose overexpression is associated with poor clinical outcome in colon cancer patients, and has a potential role in promoting tumor metastasis." (PMID 26437221, 2015). "To test this prediction, we transfected VACO-400 and SW480 colon cancer cell lines with expression vectors encoding C-terminal V5 or T7-epitope-tagged CEMIP." (PMID 26437221, 2015). "Important to this study is our finding that elevated CEMIP expression in human colon tumors is associated with markedly reduced survival in stage III colon cancer cases." (PMID 26437221, 2015). "In the present study, we have comprehensively characterized CEMIP expression in colon cancer and have provided the novel findings that CEMIP overexpression is associated with poor patient prognosis and is necessary for tumor growth." (PMID 26437221, 2015). "In testing for CEMIP somatic mutations, we identified only one mutation among 13 colon cancer cell lines, a homozygous Gly1173Asp alteration present in a single sample." (PMID 26437221, 2015). "In transcriptomic profiles from normal colonic mucosa and colorectal adenomas, there is a strong positive correlation between CEMIP expression and the Wnt/β-catenin signaling pathway, which is recapitulated in colon cancer cell lines with loss and gain of function for CEMIP." (PMID 36291875, 2022). "These IHC data suggest that CEMIP is associated with the invasive capability of colon cancer cells." (PMID 26009875, 2015). "Upregulated CEMIP has been linked with decreased survival probability in patients with colon cancer and other type of cancers, suggesting that CEMIP may be used as a prognostic marker." (PMID 26009875, 2015). "Elevated tumor CEMIP expression showed an even more statistically significant association with reduced survival in an expanded set of individuals having either stage II or stage III colon cancers." (PMID 26437221, 2015). "Our finding of an inverse association between CEMIP levels and HA deposition suggests a model in which CEMIP overexpression contributes to colon cancer phenotype both by removing a HA physical barrier as well as by increasing production of tumor promoting low molecular weight HA fragments." (PMID 26437221, 2015). "Interestingly, increased CEMIP expression in colon cancer cells correlated with the loss/relocation of E-cadherin at cell-cell adheren junctions." (PMID 26009875, 2015). "The adverse outcome associated with high CEMIP tumor expression was also evident in an analysis that combined the 31 stage III colon cancer cases with an additional 42 stage II colon cancer cases that were also microsatellite stable and had available long term follow-up." (PMID 26437221, 2015). "In colon cancer cell lines, only the 153kD species was detected, suggesting that the 100kD species is either a proteolytic fragment of the mature 150kD CEMIP molecule, or represents a yet unknown CEMIP splice variant." (PMID 26437221, 2015). "PTX, as a drug that can stabilize microtubules and inhibit the effect of CEMIP, thus, attenuated the movement of colon cancer cells." (PMID 37662915, 2023). "The knockdown of CEMIP also reduces the ability of human colon cancer cells to form xenograft tumors in athymic mice." (PMID 36291875, 2022). "Our results are in line with findings on gastric and colon cancer cells in which CEMIP activate the Wnt/β-catenin pathway." (PMID 30718510, 2019). "The role of CEMIP in colon cancer progression and mediating oncogenic growth is unclear, with studies implicating CEMIP as a target of Wnt/β-catenin signaling, and as a promoter of glycogen breakdown and cellular survival." (PMID 26437221, 2015).
colon carcinoma (continued). "Immunohistochemistry of human colon cancer tissues revealed that CEMIP is upregulated in cancer cells located at the invasive front or in the submucosa." (PMID 26009875, 2015). "Real-time PCR analysis of a second independent set of 29 colon cancer cases further confirmed CEMIP induction in colon cancers." (PMID 26437221, 2015). "In agreement with this assumption, a high incidence of positive staining of CEMIP (76%) was observed in colon cancer cells that metastasized to lymph nodes." (PMID 26009875, 2015). "In this study, we comprehensively characterize CEMIP expression in colon cancer and investigate its role in colon cancer progression and as an indicator of poor clinical outcome." (PMID 26437221, 2015). "Surprisingly, 66% of primary colon cancer specimens were negligibly stained with a well-characterized anti-CEMIP antibody, which is in contrast to a previous report of bulk colon cancer tissue specimens examined by DNA microarray." (PMID 26009875, 2015). "In this analysis, we retained the same definition of CEMIP high versus low cancers as in our original analysis (i.e. the new colon cancer cases were defined as CEMIP high or low using the same criteria of having CEMIP expression higher or lower than 1.024)." (PMID 26437221, 2015). "We present CEMIP as a candidate prognostic marker for colon cancer and a potential therapeutic target." (PMID 26437221, 2015). "CEMIP mRNA expression was measured by real-time PCR of colon cancer tumors obtained from 31 stage III colon cancer patients with microsatellite stable cancers and for whom long term clinical follow-up was available." (PMID 26437221, 2015). "In colon cancer tumors, we detected CEMIP protein at the expected ∼153kD molecular weight along with a second 100kD molecular weight species." (PMID 26437221, 2015). "Having confirmed induction of CEMIP protein expression in colon cancer cell lines, we next determined if CEMIP protein levels are upregulated in patient colon tumors." (PMID 26437221, 2015). "Using, RT-PCR we connected CEMIP to additional multiple ESTs that mapped to the 15q24-25 genomic region, finding expression in colon cancers of a 4083 bp full-length coding transcript that covers 30 exons and encodes a protein of 1361 amino acids." (PMID 26437221, 2015). "Individuals whose stage III colon cancer tumors express CEMIP below the median lived an average > 8.6 years longer than stage III colon cancer cases whose tumor CEMIP levels were above the median, a dramatic difference in patient survival." (PMID 26437221, 2015). "When individual human colon cancer specimens were examined in detail, we observed that most of the colon cancer cells located in the mucosal layer displayed minimal expression of CEMIP." (PMID 26009875, 2015). "While only two normal colon mucosal samples showed any expression of CEMIP above the microarray measurement threshold of 25, median expression of CEMIP reached 451 in colon cancer cell lines, and 330 in primary colon tumors." (PMID 26437221, 2015). "Similar to ours and others findings in colon cancer, a search of the Oncomine database identifies microarray studies demonstrating upregulation of CEMIP in several other epithelial cancers, including breast, gastric, and pancreatic cancer." (PMID 26437221, 2015). "We molecularly characterized CEMIP expression both at the mRNA and protein level and found it is a secreted protein induced an average of 54-fold in colon cancer." (PMID 26437221, 2015). "Characterization of the regulatory mechanism of CEMIP is significant because upregulated CEMIP is only detected in colon cancer cells located at the invasive front or submucosa examined by IHC." (PMID 26009875, 2015). "Colon cancer cases were divided into those with CEMIP expression above the median (CEMIP high), and those with CEMIP expression below the median (CEMIP low) (median CEMIP = 1.024)." (PMID 26437221, 2015).
colon carcinoma (continued). "Our study revealed that only 34% of TMA from colon cancer patients were positively stained for CEMIP." (PMID 26009875, 2015). "To further determine the link between hypoxia and CEMIP expression, we carried out in vitro studies using two well-characterized human colon cancer cell lines, less aggressive SW480 cells and aggressive HCT-116 cells." (PMID 26009875, 2015). "Such overexpression of CEMIP is detected in colon cancer tissues, indicating that CEMIP may be involved in the progression of local tumors." (PMID 36451490, 2022). "CEMIP has been reported to be localized at the invasive front of colon cancer tissue, and the hyaluronidase activity may conceivably contribute to tissue invasion through the degradation of HA-dependent migratory barriers." (PMID 36291875, 2022). "Notably, KIAA1199 enhances the motility of colon cancer cells and is therefore called the cell migration-inducing protein (CEMIP)." (PMID 34521918, 2021). "It has been demonstrated that CEMIP can promote prostate, breast, and colon cancer cell motility." (PMID 34966410, 2021). "Furthermore, CEMIP knockout in human colon cancer cells prevented the formation of xenograft tumors in athymic mice." (PMID 31213644, 2019). "Among the 34% of positively stained tumors, most of the cases contained colon cancer cells invading into the submucosa, suggesting CEMIP may be upregulated only in invasive colon cancer cells." (PMID 26009875, 2015). "Importantly, we linked hypoxia to a cascade of HIF-2α-Jarid1A-H3K4me3 to enhanced CEMIP transcription in colon cancer dissemination." (PMID 26009875, 2015). "Our study links upregulated CEMIP expression with colon cancer dissemination." (PMID 26009875, 2015). "The two most highly induced probesets corresponded to P-Cadherin, already known to be induced in colon cancers, and to KIAA1199 (herein called CEMIP), which was a hypothetical gene with only a partial cDNA at the time these expression array studies were performed." (PMID 26437221, 2015). "Interestingly, cell surface staining of CA9 in colon cancer cells positively correlates with cytoplasmic staining of CEMIP." (PMID 26009875, 2015). "Degradation of HA to low molecular weight fragments can stimulate angiogenesis, promote cell migration, and play an important role in cancer progression and inflammation, thus suggesting a possible functional role for the upregulation of CEMIP in the progression of colon cancer." (PMID 26437221, 2015). "Since CEMIP expression is highly upregulated in colon cancer, we examined if CEMIP expression levels might be prognostic of a patient's clinical outcome." (PMID 26437221, 2015). "Thus CEMIP overexpression is key mediator of the ability of colon cancer cells to degrade the HA component of extracellular matrix." (PMID 26437221, 2015). "However, there is controversy regarding the frequency of CEMIP upregulation in primary colon cancer." (PMID 26009875, 2015). "The marked induction of CEMIP protein in colon cancer tumors was further confirmed by immunohistochemistry, which strongly detected CEMIP protein in colon cancer cells in multiple colon cancer tumors tested, and showed absence of detectable CEMIP in each matched normal colonic mucosa." (PMID 26437221, 2015). "In stage III only (n = 31) or in combined stage II plus stage III colon cancer cases (n = 73), 5-year overall survival was significantly better (p = 0.004 and p = 0.0003, respectively) among patients with low CEMIP expressing tumors than those with high CEMIP expressing tumors." (PMID 26437221, 2015). "The inhibition of UBE2C by NSC697923 promoted CEMIP down-regulation, increasing the sensitivity to radiotherapy in the SW480 colon cancer cells." (PMID 31213644, 2019). "CEMIP, originally called KIAA1199/CCSP1, is one such gene that is highly upregulated in colon cancer." (PMID 26437221, 2015).
colon carcinoma (continued). "This conclusion is supported by a positive correlation between CEMIP expression and the hypoxia marker CA9 in human colon cancer cells as well as several lines of in vitro biochemical and biological studies." (PMID 26009875, 2015). "To interrogate the contribution of CEMIP to colon cancer phenotype, we used a gene targeting vector to knock out CEMIP in the colon cancer cell line, DLD-1, that normally expresses CEMIP at high levels." (PMID 26437221, 2015). "High levels of CEMIP were detected in early node-negative stage II colon cancers (median value 226), and in colon adenomas (1 tubular, 2 tubulovillous and 6 villous all > 1 cm in size, median value 264)." (PMID 26437221, 2015). "Clinical significance of CEMIP in cancer has been highlighted by its upregulation in numerous human cancers, including breast, gastric, and colon cancers, and its negative correlation with patient survival." (PMID 26009875, 2015). "Kaplan-Meier survival analysis for colon cancer specific death showed that CEMIP low cases (n = 15) had notably favorable outcomes, with median survival of greater than 140 months." (PMID 26437221, 2015). "In further analysis of primary colorectal tumors, 13 of 15 colon cancers demonstrated easily detectable CEMIP expression; whereas, no signal was detected in any of the 15 matched normal colon mucosa samples." (PMID 26437221, 2015). "HCT-116 cells had a significantly higher level of CEMIP expression and increased migratory ability compared to SW480 cells, suggesting a positive correlation between CEMIP expression and cell migration in colon cancer." (PMID 26009875, 2015). "Serial CEMIP immunoprecipitation and Western blot analyses from 10 cases confirmed that, identical to the CEMIP transcript, endogenous CEMIP protein is absent in normal colonic mucosa but is strongly induced in colon cancer tumors." (PMID 26437221, 2015). "CEMIP did not demonstrate focus forming activity in NIH3T3 cells (by transfection), or change in anchorage independent growth (by adding CEMIP protein), and attempts to express CEMIP protein by transfection in those rare colon cancer cell lines that did not induce CEMIP were in general unsuccessful." (PMID 26437221, 2015). "The specificity of the PW-3 monoclonal antibody for immunostaining was confirmed by PW-3 showing strong reactivity on immunostaining pellets of CEMIP transcript positive FET colon cancer cells versus no staining of CEMIP transcript negative RKO colon cancer cells." (PMID 26437221, 2015). "Northern analysis strongly confirmed that CEMIP is expressed by malignant but not normal colon tissues, with a single 7 kb CEMIP transcript of moderate to strong intensity detected in 5 of 7 colon cancer cell lines, but in none of 6 normal colon epithelial tissue samples." (PMID 26437221, 2015).
gastric cancer (23 papers, 2011 to 2025). A primary or metastatic malignant neoplasm involving the stomach. "Efforts in drug development targeting CEMIP have shown promise, revealing its role in drug resistance and its potential as a biomarker for gastric cancer detection, prognostication, and treatment response." (PMID 38390387, 2024). "CEMIP promotes the invasion and migration of gastric cancer cells by enhancing the Wnt/β-catenin pathway and matrix metalloproteinases-mediated EMT progression." (PMID 36451490, 2022). "For example, the knockdown of CEMIP in colorectal and gastric cancer cells inhibits their migration and invasiveness in vitro." (PMID 36291875, 2022). "In gastric cancer cells, CEMIP fosters the expression of several downstream targets of Wnt/β-catenin signaling, including EMT-related molecules such as snail, vimentin, N-cadherin, c-Myc, cyclin D1, and MMPs (MMP2, MMP7, and MMP14)." (PMID 36291875, 2022). "Epithelial-to-mesenchymal transition has been shown to promote metastasis of PTC, and CEMIP promoted the epithelial-to-mesenchymal transition of gastric cancer." (PMID 35543351, 2022). "Consistently, the overexpression of CEMIP in gastric cancer cells promotes tumor growth in vivo upon subcutaneous or intra-peritoneal injection." (PMID 36291875, 2022). "CEMIP is upregulated in gastric cancer tissues and correlates to poorer clinical results in gastric cancer." (PMID 36451490, 2022). "In gastric cancer, CEMIP was shown to alter the expression of MMP2, a known player in EMT progression." (PMID 35177031, 2022). "In the context of chemotherapy, the downregulation of CEMIP increases the sensitivity of resistant gastric cancer cells to the chemotherapeutic agent 5-fluorouracil (5-FU), indicating the potential utility of using CEMIP inhibitors in combination with chemotherapy." (PMID 36291875, 2022). "Again, CEMIP has also been shown to be an independent prognostic factor in NSCLC, gastric cancer, pancreatic ductal adenocarcinoma, laryngeal squamous cell carcinoma, osteosarcoma, and HCC." (PMID 36291875, 2022). "In a study of gastric cancer (GC), activating transcription factor 3 (ATF3) inhibited the activity of CEMIP promoter." (PMID 37662915, 2023).
prostate carcinoma (23 papers, 2012 to 2026). A carcinoma that arises from epithelial cells of the prostate gland. "Overall, CEMIP is a novel target for cancers and other human diseases such as CRC, CCA, and prostate cancer, further investigations on the regulation of CEMIP are awaited." (PMID 36451490, 2022). "For example, in prostate cancer cells, CEMIP physically interacts with 1,4,5-trisphosphate receptor type 3 (ITPR3), a protein that regulates intracellular Ca2+ release." (PMID 36291875, 2022). "CEMIP has been shown to enhance PDK4-mediated metabolic reprogramming to promote metastasis of prostate cancer." (PMID 35543351, 2022). "Previous studies have shown that cell migration-inducing protein (CEMIP) accelerates prostate cancer (PCa) anoikis resistance (AR) by activating autophagy." (PMID 35655258, 2022). "HCP5 enhances cell proliferation of prostate cancer by targeting the miR-4656/CEMIP axis." (PMID 35602292, 2022). "Moreover, the β-catenin-dependent upregulation of CEMIP has been reported in anoikis-resistant prostate cancer cells, although in this case via crosstalk with AMPK/GSK3β." (PMID 36291875, 2022). "Furthermore, the depletion of CEMIP in prostate cancer cells reduces the expression of pyruvate dehydrogenase kinase isoform 4 (PDK4) and lactate dehydrogenase A (LDHA), enzymes important for efficient glycolysis in tumor cells, thereby decreasing cellular pyruvate, lactate, and ATP levels." (PMID 36291875, 2022). "CEMIP over-expression, triggered by the AMPK/GSK3β/β-catenin cascade, can promote migration and invasion in anoikis-resistant prostate cancer cells by enhancing metabolic reprogramming." (PMID 41596231, 2026). "Cell-migration-inducing protein (CEMIP), also known as KIAA1199, plays a significant role in promoting anoikis resistance, especially in prostate cancer cells, often by enhancing protective autophagy." (PMID 41596231, 2026). "CEMIP promoted PDK4 to enhance the metabolic reprogramming and induce prostate cancer cell metastasis." (PMID 35543351, 2022). "Conversely, the CEMIP, HSPB1, and PANX2 genes, which interfere with the process of ferroptosis, can effectively promote the survival of prostate cancer cells, suggesting that ferroptosis-related genes may be prognostic biomarkers and potential drug targets for patients with prostate cancer." (PMID 38705987, 2024).